VPS50 (VPS50 subunit of EARP/GARPII complex)
Description:
Acts as a component of the EARP complex that is involved in endocytic recycling. The EARP complex associates with Rab4-positive endosomes and promotes recycling of internalized transferrin receptor (TFRC) to the plasma membrane. Within the EARP complex, required to tether the complex to recycling endosomes. Not involved in retrograde transport from early and late endosomes to the trans-Golgi network (TGN).
Synonyms: CCDC132; KIAA1861; FLJ20097; DKFZp313I2429; VPS54L; NEDMSC
Tractability: Antibody: the Human Protein Atlas places it where antibodies can reach. PROTAC: UniProt records ubiquitination sites on it; ubiquitination databases record sites on it; its protein half-life has been measured.
Gene: Protein-coding gene on chromosome 7 (93,232,340 to 93,361,123, forward strand). Ensembl gene ENSG00000004766.
Subcellular location: Recycling endosome; Membrane
Subcellular location (Human Protein Atlas): Cytosol; Plasma membrane; Basal body; End piece; Mid piece; Primary cilium; Principal piece
Gene Ontology:
Molecular function: protein binding; SNARE binding
Biological process: endocytic recycling; retrograde transport, endosome to Golgi
Cellular component: EARP complex; extracellular exosome; membrane; recycling endosome; perinuclear region of cytoplasm
Genetic constraint (gnomAD): Loss-of-function variants: 10 observed, 21.73 expected, observed/expected ratio (o/e) 0.46, 90% interval 0.28 to 0.78. The upper end of that interval is the gene's LOEUF score, 0.78, which puts it in group 3 of 6, group 1 being the genes least tolerant of losing a copy. Missense variants: 163 observed, 211.22 expected, observed/expected ratio (o/e) 0.77, 90% interval 0.68 to 0.88. Synonymous variants: 69 observed, 68.55 expected, observed/expected ratio (o/e) 1.01, 90% interval 0.83 to 1.23.
Homologues: Orthologues: chimpanzee VPS50 (99% identical), macaque VPS50 (99% identical), dog VPS50 (99% identical), pig VPS50 (98% identical), rabbit VPS50 (98% identical), rat Vps50 (96% identical), mouse Vps50 (96% identical), guinea pig VPS50 (93% identical), tropical clawed frog vps50 (88% identical), zebrafish vps50 (84% identical), Drosophila melanogaster Vps50 (32% identical), Caenorhabditis elegans vps-50 (29% identical), and 1 more.
Diseases named in the same sentence as VPS50 in open-access papers:
VPS50 is named in the same sentence as 14 diseases in open-access papers, as found by Europe PMC text mining. Sharing a sentence is not in itself a finding about the gene and the disease. The quoted sentences say what the papers report.
autism spectrum disorder (1 paper, 2024). A spectrum of developmental disorders that includes autism, and Asperger syndrome. "Patients with mutations in VPS50 show severe developmental delay and intellectual disability, characteristics that have been associated with autism spectrum disorders (ASDs)." (PMID 38926759, 2024).
cognitive deficits (1 paper, 2024). "In mice, mosaic KO of VPS50 in the hippocampus altered synaptic transmission and plasticity and generated robust cognitive impairments." (PMID 38926759, 2024). "Our findings suggest mechanisms through which VPS50 mutations contribute to ASD phenotypes in general and to cognitive impairment in particular." (PMID 38926759, 2024). "Deficits in this process, as exhibited by VPS50 mKO mice, result in cognitive impairment." (PMID 38926759, 2024). "Our findings shed light on the molecular mechanisms underlying VPS50’s function and highlight the significance of VPS50 in maintaining synaptic transmission integrity, as evidenced by the impaired synaptic activity and cognitive deficits observed in VPS50 mKO mice." (PMID 38926759, 2024).
congenital hydrocephalus (1 paper, 2023). Hydrocephalus that is present at birth. "We also highlight an apparently novel recessive allelic disorder caused by homozygous LOF in VPS50 and comprises severe congenital hydrocephalus in family F9792 (no biallelic LOF variants have been reported before, which may explain the severe nature of this phenotype)." (PMID 37644014, 2023).
depression (1 paper, 2022). "These human data, therefore, suggest a potential link between BLM-s/VPS50 gene variants and human depression traits." (PMID 36163151, 2022). "Although BLM-s or its isoforms BLM-l (VPS50) is not in the list of candidate genes and variants for major MDD studies, our analysis of UK biobank does reveal that human VPS50 rs2285505 and rs17147430 variants are statistically significantly associated with increased depression in mood domain." (PMID 36163151, 2022). "Interestingly, certain genetic variants of the human Blm homologue gene (VPS50) are significantly associated with depression traits from publicly resourced UK Biobank data." (PMID 36163151, 2022).
developmental delays (1 paper, 2024). "More recently, two patients with a neurodevelopmental disorder including severe developmental delays and intellectual disability were reported to carry homozygous loss-of-function mutations in Vps50." (PMID 38926759, 2024).
autosomal recessive disease (1 paper, 2023). Autosomal recessive form of disease. "With our study, we provided Moderate or Strong level of evidence for GDR for 11 genes that were not listed in OMIM as having phenotype entity: FBRSL1, AGR2, ACBD6, C1orf127, PAN2, VPS50, KCTD3, NOTCH3 (for autosomal recessive disease), FAT1, NRAP, and SCLT1." (PMID 39669245, 2023).
infection (1 paper, 2024). The state of being infected such as from the introduction of a foreign agent such as serum, vaccine, antigenic substance or organism. "Cortical neuron cultures from Cas9 KI mice were transduced at 3 DIV with AAV encoding tdTomato as an infection marker alone or together with sgRNAs targeting the Vps50 gene." (PMID 38926759, 2024).
VPS50 also shares sentences with these, for which no sentence is quoted: neurodevelopmental disorder (2 papers); breast carcinoma (1); cancer (1); Intellectual disability (1); microcephaly (1); pancreatitis (1); Primary microcephaly (1).